RNF19A (ring finger protein 19A, RBR E3 ubiquitin protein ligase)
Description:
E3 ubiquitin-protein ligase which accepts ubiquitin from E2 ubiquitin-conjugating enzymes UBE2L3 and UBE2L6 in the form of a thioester and then directly transfers the ubiquitin to targeted substrates, such as SNCAIP or CASR. Specifically ubiquitinates pathogenic SOD1 variants, which leads to their proteasomal degradation and to neuronal protection.
Synonyms: Dorfin; RNF19; DKFZp566B1346
Tractability: Antibody: UniProt predicts a signal peptide or a membrane-spanning region. PROTAC: ubiquitination databases record sites on it.
Gene: Protein-coding gene on chromosome 8 (100,257,059 to 100,336,218, reverse strand). Ensembl gene ENSG00000034677.
Subcellular location: Membrane; Cytoplasm, cytoskeleton, microtubule organizing center, centrosome
Pathways (Reactome):
Immune System: Antigen processing: Ubiquitination & Proteasome degradation
Gene Ontology:
Molecular function: protein binding; ubiquitin conjugating enzyme binding; ubiquitin protein ligase activity; ubiquitin-protein transferase activity; zinc ion binding
Biological process: microtubule cytoskeleton organization; protein ubiquitination
Cellular component: centrosome; cytosol; ubiquitin ligase complex; membrane
Genetic constraint (gnomAD): Loss-of-function variants: 29 observed, 73.12 expected, observed/expected ratio (o/e) 0.4, 90% interval 0.29 to 0.54. The upper end of that interval is the gene's LOEUF score, 0.54, which puts it in group 2 of 6, group 1 being the genes least tolerant of losing a copy. Missense variants: 763 observed, 1,055.7 expected, observed/expected ratio (o/e) 0.72, 90% interval 0.68 to 0.77. Synonymous variants: 328 observed, 352.11 expected, observed/expected ratio (o/e) 0.93, 90% interval 0.85 to 1.02.
Homologues: Orthologues: chimpanzee RNF19A (100% identical), macaque RNF19A (99% identical), dog RNF19A (98% identical), pig RNF19A (97% identical), rabbit RNF19A (97% identical), guinea pig RNF19A (96% identical), mouse Rnf19a (94% identical), rat Rnf19a (93% identical), tropical clawed frog rnf19a (84% identical), zebrafish rnf19a (75% identical), mouse Gm65991 (75% identical), Caenorhabditis elegans C17H11.6 (34% identical), and 1 more. Paralogues in human: RNF19B (48% identical), ANKIB1 (18% identical), ARIH1 (12% identical), RNF144A (11% identical), ARIH2 (10% identical), RNF144B (10% identical), RNF14 (9% identical), PRKN (9% identical), RNF217 (8% identical).
Diseases named in the same sentence as RNF19A in open-access papers:
RNF19A is named in the same sentence as 21 diseases in open-access papers, as found by Europe PMC text mining. Sharing a sentence is not in itself a finding about the gene and the disease. The quoted sentences say what the papers report.
Parkinson disease (4 papers, 2018 to 2023). A progressive degenerative disorder of the central nervous system characterized by loss of dopamine producing neurons in the substantia nigra and the presence of Lewy bodies in the substantia nigra and locus coeruleus. "RNF19A has previously been implicated in Parkinson’s disease in which there is slowed information processing and in amyotrophic lateral sclerosis." (PMID 34864818, 2021). "It has been established that the RNF19A gene mainly plays a role in neurons causing amyotrophic lateral sclerosis or Parkinson’s disease." (PMID 29659518, 2018). "A previous study shows that RNF19A is related to familial amyotrophic lateral sclerosis and Parkinson’s disease and inhibits neuron phenotype and motor neuron death." (PMID 37326687, 2023). "Further, an important gene is RNF19A, which encodes the protein E3 ubiquitin ligase localized to Lewy bodies, which may be involved in ALS and Parkinson's disease." (PMID 37337823, 2023). "RNF19A is a RING finger-type E3 ubiquitin ligase that has been shown to localize to Lewy bodies, a characteristic neuronal inclusion in the brain of patients with Parkinson’s disease, and to ubiquitylate synphylin-1." (PMID 34864818, 2021).
amyotrophic lateral sclerosis (3 papers, 2015 to 2021). Amyotrophic lateral sclerosis (ALS) is a neurodegenerative disease characterized by progressive muscular paralysis reflecting degeneration of motor neurons in the primary motor cortex, corticospinal tracts, brainstem and spinal cord. "RNF19A also appears to play a role in familial amyotrophic lateral sclerosis (ALS) by ubiquitylating mutant superoxide dismutase (SOD-1) proteins and promoting their degradation, thereby contributing to the protection of surviving motor neurons." (PMID 34864818, 2021). "Dorfin, also known as Rnf19a, is a RING finger E3 ubiquitin ligase implicated in amyotrophic lateral sclerosis and Parkinson’s disease, but its in vivo functions have not been explored." (PMID 26553645, 2015).
prostate carcinoma (3 papers, 2012 to 2024). A carcinoma that arises from epithelial cells of the prostate gland. "For example, RNF19A mRNA was amplified in the blood of prostate cancer patients and RNF19A is aberrantly expressed in cancer-related fibroblast." (PMID 34789768, 2021). "Quantitative RT-PCR analysis confirmed a more than 2-fold higher level of RNF19A mRNA levels in the blood of patients with prostate cancer than in healthy controls (p = 0.0066)." (PMID 22493721, 2012). "The Ring finger protein 19A (RNF19A) transcript was identified as having higher levels in prostate cancer patients compared to healthy men through the averaged differential display process." (PMID 22493721, 2012). "In this study, we describe the use of ADE to identify an RNA transcript, RNF19A (Gene ID: 25897), that is present at higher levels in the blood of prostate cancer patients than in healthy controls." (PMID 22493721, 2012). "Furthermore, this proof-of-concept study warrants further analysis of RNF19A as a clinically relevant biomarker for prostate cancer detection." (PMID 22493721, 2012).
breast carcinoma (2 papers, 2021 to 2022). "We provide evidence that high RNF19A expression in breast cancer compromises HR and increases sensitivity to PARPi." (PMID 34789768, 2021).
lung carcinoma (2 papers, 2020 to 2021). "The expression pattern, biological functions and the related mechanisms of the ring finger protein 19A (RNF19A) in non‐small cell lung cancer (NSCLC) remain poorly understood." (PMID 34184814, 2021).
Alzheimer disease (1 paper, 2021). A progressive, neurodegenerative disease characterized by loss of function and death of nerve cells in several areas of the brain leading to loss of cognitive function such as memory and language. "The results of the network analysis suggest that RNF19A may play a role in embryonic development, and interacts with several genes that have been identified in GWAS of either Alzheimer’s disease or vascular risk factors associated with cognitive decline in late life." (PMID 34864818, 2021).
glioblastoma multiforme (1 paper, 2022). "Consistent with our previous findings, the expressions of NUP107, DRAM1, RNF19A, PXDN, HEY2, F2R, and BMP2 were up-regulated in gliomas (glioblastoma multiforme + lower grade glioma)." (PMID 36245971, 2022).
glioma (1 paper, 2022). A benign or malignant brain and spinal cord tumor that arises from glial cells (astrocytes, oligodendrocytes, ependymal cells). "BMP2 and HEY2 were identified as protective factors (HR < 1), and NUP107, DRAM1, F2R, PXDN, RNF19A, and SCG5 were identified as risk factors for glioma (HR > 1)." (PMID 36245971, 2022). "In our study, the results of human tissue-based IHC staining and QRT-PCR experiments well confirmed the biological value of F2R, HEY2, PXDN, RNF19A, SCG5, and DRAM1 in glioma." (PMID 36245971, 2022).
non-small cell lung carcinoma (1 paper, 2022). A group of at least three distinct histological types of lung cancer, including non-small cell squamous cell carcinoma, adenocarcinoma, and large cell carcinoma.
Sepsis (1 paper, 2023). Sepsis is defined as life-threatening organ dysfunction caused by a dysregulated host response to infection. "In this study, we mainly explored the functionality of BMMSC-derived exosomal KCNQ10T1 and its potential interactions with the miR-154-3p/RNF19A axis in sepsis." (PMID 37326687, 2023). "Our study demonstrates that the exosomal KCNQ1OT1 suppresses sepsis via mediating miR-154-3p/RNF19A, which provides a latent target for sepsis treatment." (PMID 37326687, 2023). "In our study, we confirmed that RNF19A was significantly down-regulated in the sepsis model and that RNF19A was the downstream target gene of miR-154-3p involved in sepsis." (PMID 37326687, 2023). "We found that KCNQ10T1 was down-regulated in the sepsis model and might regulate the miR-154-3p/RNF19A axis to participate in the regulation of sepsis progression." (PMID 37326687, 2023). "It was speculated that exosomal KCNQ1OT1 might play a vital role in the progression of sepsis by targeting the miR-154-3p/RNF19A axis." (PMID 37326687, 2023). "To further explore the interaction relationship between KCNQ1OT1, miR-154-3p, and RNF19A in the progression of sepsis, we transfected HUVEC cells with sh-KCNQ1OT1 + NC-inhibitor or sh-KCNQ1OT1 + miR-154-3p inhibitor or sh-KCNQ1OT1 + miR-154-3p inhibitor + sh-RNF19A." (PMID 37326687, 2023). "Further quantitative analysis showed that only the RNF19A mRNA level was significantly reduced, suggesting that RNF19A might be the target gene of miR-154-3p involved in sepsis." (PMID 37326687, 2023). "Importantly, functional research findings indicated that KCNQ1OT1 regulated sepsis progression by targeting miR-154-3p/RNF19A axis." (PMID 37326687, 2023). "Moreover, the rescue experiment suggested that KCNQ10T1 inhibited sepsis progression by targeting the miR-154-3p/RNF19A axis." (PMID 37326687, 2023). "In addition, to further confirm the roles of LncRNA-KCNQ1OT1, miR-154-3p, and RNF19A in sepsis, it might make the results more convincing to further reverse the study of the effects of high expression LncRNA-KCNQ1OT1/miR-154-3p/RNF19A on sepsis model in rescue experiments." (PMID 37326687, 2023).
small cell lung carcinoma (1 paper, 2024). Small cell lung cancer (SCLC) is a highly aggressive malignant neoplasm, accounting for 10-15% of lung cancer cases, characterized byrapid growth, and early metastasis.
cancer (5 papers, 2012 to 2024). A tumor composed of atypical neoplastic, often pleomorphic cells that invade other tissues. "Emerging evidence has shown the association between RNF19A and cancers." (PMID 34789768, 2021). "Our results elucidate how RNF19A-mediated ubiquitylation of BARD1 induces dissociation of BRCA1, unmasks the NES region of BARD1, restrains HR activity, and makes cancer cells more susceptible to PARPi treatment." (PMID 34789768, 2021). "We propose that RNF19A modulates the cancer cell response to PARPi by negatively regulating the BRCA1-BARD1 complex and inhibiting HR-mediated DNA repair." (PMID 34789768, 2021). "Here, we show that cancer cell sensitivity to PARPi is promoted by the ring between ring fingers (RBR) protein RNF19A." (PMID 34789768, 2021). "The accuracy of distinguishing cancer patients from healthy men using RNF19A mRNA levels in blood as determined by the area under the receiving operator curve was 0.727." (PMID 22493721, 2012). "Notably, the amplification of RNF19A mRNA is a common phenomenon in many human cancers, suggesting a specific role for RNF19A in cancer." (PMID 39567496, 2024). "To investigate the clinical relevance of RNF19A in cancer, we first examined whether RNF19A impacts BC response to chemotherapy." (PMID 34789768, 2021). "Importantly, RNF19A WT, but not RNF19A R1, was able to reverse the increase in HR repair caused by RNF19A deficiency and re-sensitize cells to PARPi, suggesting that the RNF19A/BARD1 interaction is essential for HR regulation and cancer cell response to PARPi." (PMID 34789768, 2021). "However, the functions and mechanisms of RNF19A in cancer remain largely unknown." (PMID 39567496, 2024). "Rnf19a, a member of RING-in-between-RING (RBR) E3 ligases which has been reported to be involved in inflammation regulation, cancers, spermiogenesis, neurogenesis, synaptic plasticity and contextual fear memory, was selected for further study." (PMID 37480121, 2023). "However, the detailed function of RNF19A in cancer remains unclear." (PMID 34789768, 2021). "Overexpression of RNF19A slightly promoted cancer cell growth without drug intervention while mice bearing RNF19A overexpressing MDA-MB-231 cells displayed more noticeable tumor shrinkage in the Olaparib treatment group." (PMID 34789768, 2021). "Here we identify that RNF19A, a ring between ring fingers (RBR) family E3 ligase, interacts with and ubiquitinates BARD1, resulting in the nuclear export of BARD1, thus compromising HR and sensitizing cancer cells to PARPi." (PMID 34789768, 2021). "To further test whether RNF19A has a role in the DDR, we knocked down RNF19A and found cancer cells were more resistant to DNA-damaging agents, including Olaparib, Cisplatin, and IR, whereas ectopically expressed WT RNF19A reversed this phenomenon." (PMID 34789768, 2021). "However, to date, there are no studies on the intracellular RNF19A expression pattern, as well as its direct role and mechanism, in cancers." (PMID 34184814, 2021).
tumor (4 papers, 2021 to 2024). "The chi‐squared test indicated that high RNF19A expression was notably associated with tumour size (P < .05) and TNM stage (P < .05) of patients with NSCLC." (PMID 34184814, 2021). "Western blotting revealed wild-type RNF19A at ~90 kDa, and an immune band at ~50 kDa was also observed in 10 pairs of PCa tumor samples and adjacent normal prostate tissue samples." (PMID 39567496, 2024). "The difference in RNF19A staining between tumor and adjacent tissues was statistically significant, consisting of the mRNA expression results from our database search." (PMID 34789768, 2021). "Compared with those in HBE cells, RNF19A levels were mostly elevated in tumour cell lines." (PMID 34184814, 2021). "Moreover, a negative correlation between increased RNF19A and decreased percentage of nuclear BARD1 was observed in tumor tissues." (PMID 34789768, 2021). "Indeed, we observed a negative correlation between RNF19A expression and nuclear/cytoplasm ratio of BARD1, which is lower in tumor tissues compared with adjacent tissues." (PMID 34789768, 2021).
infection (1 paper, 2023). The state of being infected such as from the introduction of a foreign agent such as serum, vaccine, antigenic substance or organism. "Collectively, these results indicate that infection with JEV leads to a decrease in the expression of Rnf19a due to an increase in its H3K27me3 modification, which ultimately regulates the degradation of RIG-I." (PMID 37480121, 2023).
RNF19A also shares sentences with these, for which no sentence is quoted: familial amyotrophic lateral sclerosis (2 papers); autism spectrum disorder (1); breast tumor (1); cognitive decline (1); neurodegenerative disease (1); ovarian carcinoma (1); Rett syndrome (1).